FTO (FTO alpha-ketoglutarate dependent dioxygenase)
Diseases named in the same sentence as FTO in open-access papers (continued):
Sharing a sentence is not in itself a finding about the gene and the disease.
non-small cell lung carcinoma (10 papers, 2021 to 2025). A group of at least three distinct histological types of lung cancer, including non-small cell squamous cell carcinoma, adenocarcinoma, and large cell carcinoma. "However, by focusing on genes linked to lipid peroxidation, both ALKBH5 and FTO can also induce ferroptosis in non-small cell lung cancer (NSCLC) and oral squamous cell carcinoma." (PMID 40271153, 2025). "In this study, we seek to explore the role of FTO in non-small cell lung cancer (NSCLC) tumorigenicity and its relationship with epidermal growth factor receptor (EGFR) tyrosine kinase resistance." (PMID 40722726, 2025). "In non-small cell lung cancer, FTO has been demonstrated to enhance tumor proliferation through multiple m6A-dependent mechanisms, including activation of KRAS signaling and upregulation of USP7 and MZF1." (PMID 39773744, 2025). "hsa_circ_0072309 promotes tumorigenesis and invasion in non-small cell lung carcinoma by regulating miR-607/FTO axis." (PMID 35858900, 2022). "FTO was found upregulated in human non-small cell lung cancer (NSCLC) cells increasing their rate of proliferation." (PMID 33814008, 2021). "To study whether FTO participates in tumor progression of non-small cell lung cancers and exhibits prognostic potential, we studied FTO expression in lung tissues of patients diagnosed at different tumor stages." (PMID 40722726, 2025). "Hence, high expression of FTO at the gene and protein level in EGFR-TKI-resistant cell lines strongly suggests that FTO plays a role in the development of EGFR TKI resistance in non-small cell lung cancer cells." (PMID 40722726, 2025). "In this study, we demonstrated that FTO played an important role in tumor proliferation and cell migration, as well as mediating EGFR TKI resistance in non-small cell lung cancer." (PMID 40722726, 2025). "Mechanistic analyses revealed two functional targets of FTO; first, upregulation of Myeloid Zinc Finger Protein 1 (MZF1) in lung squamous cell carcinoma (LUSC), and second: ubiquitin-specific protease-7 (USP7) in non-small cell lung cancer (NSCLC)." (PMID 35409166, 2022).
renal cell carcinoma (10 papers, 2020 to 2025). "The decreased FTO mRNA levels had been proved to be associated with a poor prognosis of renal cell carcinoma." (PMID 36619747, 2022). "In 769-P renal cell carcinoma cells, overexpression of FTO leads to the upregulation of PGC1A, TFAM, and NRF1 genes, which are involved in mitochondrial biogenesis." (PMID 40361322, 2025). "The fat mass and obesity-associated protein (FTO) and alkB homolog 5 RNA demethylase (ALKBH5) are RNA-demethylating proteins that have contrasting effects in renal cell carcinoma (RCC) among different populations." (PMID 40361322, 2025). "The fat mass and obesity-associated protein (FTO) and alkB homolog 5 (ALKBH5), two RNA demethylases, have opposing effects on renal cell carcinoma (RCC)." (PMID 40361322, 2025). "Conversely, renal cell carcinoma with clear cells is a disease that is facilitated by the m6A eraser FTO-mediated autophagy through the FTO/autophagy/SIK2 axis." (PMID 38649860, 2024). "Although the role of FTO in renal cell carcinoma has been widely noted, further studies are needed to explain the controversy and to determine its role in this disease." (PMID 37865763, 2023). "In another study, the expression of FTO was also found to be down‐regulated in renal cell carcinoma, and FTO suppressed carcinogenesis of renal cell carcinoma via the FTO‐PGC‐1α signalling axis." (PMID 32808488, 2020). "In addition, clinical data analysis showed that the expression of FTO correlated negatively with adverse events in patient with renal cell carcinoma." (PMID 36860916, 2023). "In contrast, both m6A methyltransferases (METTL3 and METTL14) and m6A demethylases (FTO) act as tumour suppressor genes in renal cell carcinoma, indicating that the recruited m6A‐binding protein and potential downstream target play important roles in tumour development." (PMID 32808488, 2020). "Interestingly, the down‐regulated expression of ALKBH5 and FTO was found to be related to poor overall survival and cancer‐specific survival in renal cell carcinoma, which implied that ALKBH5 and FTO could serve as potential prognostic biomarkers." (PMID 32808488, 2020).
schizophrenia (10 papers, 2014 to 2025). A major psychotic disorder characterized by abnormalities in the perception or expression of reality. "Recent genetic studies revealed that four polymorphic variants in the FTO gene were associated with body mass index in schizophrenia patients." (PMID 37175269, 2023). "The FTO gene polymorphisms, especially rs9939609, seem to be related to weight gain after risperidone treatment in Chinese Han patients with first episode schizophrenia." (PMID 25278160, 2014). "It was found that FTO gene polymorphism, especially rs9939609, may be associated with weight gain after risperidone treatment in Han Chinese patients with first-episode schizophrenia." (PMID 35528183, 2022). "The aim of this study was to examine the relationship between FTO gene polymorphisms (rs9939609, rs8050136, rs1421085 and rs9930506) and weight gain after 6 months of risperidone monotherapy in drug-naïve, Chinese Han patients with schizophrenia." (PMID 25278160, 2014). "Our findings suggest that FTO SNP rs9939609 seem to be related to weight gain after risperidone treatment in Chinese Han patients with first episode schizophrenia." (PMID 25278160, 2014). "The CHRNA3/5 SNP (rs951266) mainly impacts lifespan through smoking and schizophrenia predisposition; the SNX29 SNP rs729583 seems to have little impact on most of the 11 traits; the FTO SNP rs9939973 essentially exerts its effect on BMI and its downstream traits." (PMID 28748955, 2017).
asthma (9 papers, 2014 to 2025). "The estimated RR for the effect of BMI on asthma at 71⁄2 y was 1.83 (95% CI 0.77–4.39) when using the FTO variant alone as an IV, and 1.50 (95% CI 1.10–2.04) when using an allele score based on the other 31 SNPs." (PMID 24983943, 2014). "FTO gene was associated with BMI and asthma 8 and appeared downregulated in asthma." (PMID 39159917, 2025). "Using the small-molecule inhibitor FB23, they demonstrated that inhibiting FTO alleviates allergic inflammation in both in vitro epithelial cell models and an in vivo house dust mite-induced asthma mouse mode." (PMID 41008562, 2025). "Knockout of the FTO gene in mouse lung tissue cells resulted in significant asthma-like inflammation in mice, as evidenced by upregulation of Th2 cell marker IL13 mRNA levels and downregulation of Th1 cell marker IL12b and the T cell antibody CD8b1." (PMID 39108751, 2024). "FTO plays a critical role in modulating asthma exacerbation induced by PM 2.5 exposure." (PMID 41008562, 2025). "FTO targets macrophage polarization and inflammatory responses and may influence the mechanism of asthma subtype formation in different microenvironments." (PMID 39108751, 2024). "The deficiency of FTO caused the destabilization of FOXJ1 mRNA, which governs the expression of a critical transcription factor essential for ciliary function, consequently displaying potent asthma‐like features." (PMID 38706740, 2024). "The results showed that the expression of known m6A writers (i.e., METTL3 and METTL14), erasers (i.e., FTO and ALKBH5), and readers (i.e., YTHDF3) was moderately downregulated in peripheral blood mononuclear cells (PBMCs) of human asthma sufferers." (PMID 37957139, 2023). "Additionally, the m6A RNA modification machinery including METTL3, METTL14, FTO, YTHDF1/2, IGF2BP2, and WTAP is explored for its emerging significance in regulating post-transcriptional gene expression during asthma progression." (PMID 41008562, 2025). "The process of FTO demethylation serves to stabilize FOXJ1 mRNA, promoting the development of motile cilia and subsequently suppressing the occurrence and advancement of asthma." (PMID 38706740, 2024). "FTO, ALKBH5, and METTL14 are thought to regulate T-cell differentiation and inflammatory response, thus having a potential role in the mechanism of different subtypes of asthma disease." (PMID 39108751, 2024). "Considered together, the m6A regulators YTHDF3, YTHDC1, WTAP, FTO, METTL3, and ETTL14 may have a significant effect on the prognosis of asthma, but studies on m6A methylation, severe asthma, and the prognosis of asthma are still in the initial stage and require further exploration by researchers." (PMID 39108751, 2024).
dementia (9 papers, 2015 to 2025). Loss of intellectual abilities interfering with an individual's social and occupational functions. "Previous studies have reported that FTO is associated with structural brain atrophy in healthy elderly subjects, and a prospective cohort study also found that FTO interacts with apolipoprotein E (APOE) to increase the risk of dementia, especially AD." (PMID 35518355, 2022). "They further figured out that FTO's effect on dementia or AD risk mainly was through interaction with the APOE ɛ4 allele." (PMID 34461609, 2021). "Several lines of evidence link genetic variations in the FTO gene with a greater risk of Alzheimer’s disease (AD) and related dementias." (PMID 32984403, 2020). "Likewise, a significant association between the FTO rs9939609 variant (AA genotype) and both AD and dementia was demonstrated by Keller and colleagues as part of the Kungsholmen project." (PMID 38790190, 2024). "A prospective cohort study showed us that carriers of FTO allele who were also carriers of apolipoprotein-E (APOE) ε4 allele have an increased risk of AD and dementia." (PMID 38255204, 2024). "It proved that those carrying genes of both FTO and AOPE ɛ4 had an increased risk for dementia." (PMID 34461609, 2021). "Furthermore, an interaction between FTO and APOE was found, with increased risk for dementia for those carrying both FTO AA and APOE ε4." (PMID 26691922, 2015). "Furthermore, these authors also discovered an interaction effect between the FTO AA and APOE ε4 genotypes that increased the risk of both AD and dementia independent of other potentially confounding factors, such as diabetes, physical activity, and BMI." (PMID 38790190, 2024).
diabetic nephropathy (9 papers, 2010 to 2025). "CKD progression demonstrates FTO’s association with patient mortality and chronic nephritis pathogenesis, while DKD involves METTL3/METTL14-mediated gene networks and FTO polymorphisms influencing diabetic nephropathy susceptibility." (PMID 40895041, 2025). "Emerging studies link dysregulated m6A machinery to diverse kidney diseases, including acute/chronic kidney injury (WTAP/METTL3/FTO in oxidative stress and fibrosis), and diabetic nephropathy (METTL14/FTO polymorphisms in susceptibility)." (PMID 40895041, 2025). "RNA sequencing showed significant associations of variants in FTO and T2D and diabetic nephropathy (DN)." (PMID 39296713, 2024). "After integrating stage-1 and stage-2 data, we identified one SNP locus, significantly associated with diabetic nephropathy; rs56094641 in FTO, P = 7.74 × 10−10." (PMID 30566433, 2018). "One SNP locus, FTO locus, showed a significant association with susceptibility to diabetic nephropathy, and the association attained a genome-wide significant level." (PMID 30566433, 2018). "In the present study, we have conducted a genetic association study of this FTO genetic polymorphism with diabetic nephropathy in type 1 diabetes using a well-characterized material selected from Genetics of Kidney Diseases in Diabetes (GoKinD) study." (PMID 20467478, 2010). "We further performed a GWAS meta-analysis for diabetic nephropathy including patients with microalbuminuria as cases, and found that rs56094641 in FTO was significantly associated with diabetic nephropathy also in this analysis (P = 2.40 × 10−9, OR = 1.18, 95% CI 1.15−1.31)." (PMID 30566433, 2018). "Therefore, our report is the first to show a robust association of FTO variant with diabetic nephropathy." (PMID 30566433, 2018). "However, the association was not stronger than that in the analysis using overt nephropathy as cases, suggesting the FTO variant was associated with advanced stages of diabetic nephropathy." (PMID 30566433, 2018). "We thus conducted a genetic association study to evaluate whether the FTO gene confers the risk susceptibility to the development of diabetic nephropathy." (PMID 20467478, 2010). "However, it is unclear whether the FTO gene confers the risk susceptibility to the development of diabetic nephropathy." (PMID 20467478, 2010). "In DKD, emerging evidence shows altered m6A marks in patients: diabetic nephropathy patients exhibit reduced global m6A levels in urine and blood, alongside decreased FTO expression." (PMID 40895041, 2025). "FTO was described to promote the progression of diabetic nephropathy, and several SNPs in the FTO gene were associated with a significantly lower risk of nephropathy in T2DM patients." (PMID 39744011, 2024). "The present study provides evidence that the common FTO genetic polymorphism, rs9939609, is associated with increased BMI in type 1 diabetes but not with diabetic nephropathy." (PMID 20467478, 2010). "Genotyping experiments of the common FTO polymorphism, rs9939609, in 1170 type 1 diabetes patients with (n = 597) or without diabetic nephropathy (n = 573) were performed with TaqMan allelic discrimination." (PMID 20467478, 2010). "Therefore, it is necessary to carry out a genetic study of the FTO gene in diabetic nephropathy." (PMID 20467478, 2010).
epilepsy (9 papers, 2022 to 2025). A brain disorder characterized by episodes of abnormally increased neuronal discharge resulting in transient episodes of sensory or motor neurological dysfunction, or psychic dysfunction. "Overexpression of FTO could alleviate epilepsy susceptibility and brain damage through mediating epigenetic up‐regulation of m6A in mice with PTE." (PMID 40534269, 2025). "For instance, FTO downregulation promotes neuronal damage and exacerbates epilepsy progression, while METTL3 inhibition can reduce neuronal injury." (PMID 40624693, 2025). "Studies have shown that m6A-related enzymes, such as METTL3, FTO, and ALKBH5, influence epilepsy progression through their effects on gene expression linked to neuronal excitability, synaptic transmission, and oxidative stress." (PMID 40624693, 2025). "Numerous preclinical evidence reported that altered FTO expression is partially responsible for energy balance, epilepsy, neurodevelopment, and neurodegenerative diseases." (PMID 36163017, 2022). "Although the exact mechanisms by which medication 7d stops seizures are yet unknown, this finding emphasizes the possibility of reducing FTO in the treatment of epilepsy." (PMID 40530256, 2025). "In an epilepsy model, Nrf2 and FTO levels were down-regulated." (PMID 39192357, 2024). "We also detected elevated levels of both FTO and ALKBH5 in human TLE, both of which have been reported to remove m6A, suggesting a more complex and nuanced regulation of m6A in human epilepsy than in mouse." (PMID 40693462, 2025). "Overall, in both mouse and human epilepsy, there are changes in the abundance of enzymes regulating m6A (notably METTL3 in both mouse and human and FTO and ALKBH5 in human TLE), although no gross changes in m6A were detectable using colorimetric assays." (PMID 40693462, 2025).
gestational diabetes (9 papers, 2017 to 2026). Carbohydrate intolerance first diagnosed during pregnancy. "The most representative SNP in FTO is rs9939609 (T>A) which has been linked with BMI, T2DM, gestational diabetes (GDM), and eating behavior." (PMID 35565885, 2022). "We excluded five meta-analyses or reviews, three articles that explored the association between FTO polymorphisms and gestational diabetes, two articles that did not include the full text, and three papers with insufficient data." (PMID 28208657, 2017). "This study investigates FTO-dependent m6A methylation in fetal programming of cardiac dysfunction due to gestational diabetes mellitus (GDM)." (PMID 41509912, 2026).
Glucose intolerance (9 papers, 2010 to 2025). Glucose intolerance (GI) can be defined as dysglycemia that comprises both prediabetes and diabetes. "Nenja showed that the loss of endothelial FTO protected mice from high-fat diet-induced glucose intolerance and IR." (PMID 35933406, 2022). "Pancreatic FTO protein was found only in islets of Langerhans, which could be associated with glucose intolerance." (PMID 37200795, 2023). "In contrast, FTO overexpression results in a dose-dependent increase in BMI and develop glucose intolerance on high-fat diet." (PMID 22697793, 2012).
myocardial ischemia (9 papers, 2021 to 2025). A disorder of cardiac function caused by insufficient blood flow to the muscle tissue of the heart. "FTO decreased the stability of Cbl Proto-Oncogene (CBL) mRNA by inhibiting m6A modification and the CBL-mediated ubiquitination and subsequent degradation of β-catenin were implicated in the suppression of pyroptosis induced by FTO during myocardial ischemia/reperfusion (I/R) injury." (PMID 39869517, 2025). "Aging-associated FTO downregulation might be associated with impaired myocardial ischemia tolerance in elderly patients." (PMID 34413770, 2021). "GSK3 stimulates FTO phosphorylation during myocardial ischemia/reperfusion (MI/R) damage, which increases FTO ubiquitination and degradation." (PMID 40919129, 2025). "However, it's important to note the possibility that the regulation of FTO in the heart could vary with age: downregulation of FTO levels was observed in response to acute myocardial ischemia-reperfusion injury in elderly murine hearts but remained unaffected in young hearts." (PMID 39744011, 2024). "FTO inhibits NLRP3-mediated pyroptosis through the suppression of β-catenin ubiquitination and degradation by decreasing the stability of CBL mRNA, contributing to the alleviation of cardiac ischemia/reperfusion injury." (PMID 38663914, 2024). "The phosphorylation of FTO by GSK-3β and the subsequent degradation of FTO by ubiquitination downregulates the expression of the transcription factor Myc during myocardial ischemia/reperfusion injury, elevating cardiomyocyte apoptosis and oxidative stress levels." (PMID 35897696, 2022).